ALG5 (ALG5 dolichyl-phosphate beta-glucosyltransferase)
Description:
Dolichyl-phosphate beta-glucosyltransferase that operates in the biosynthetic pathway of dolichol-linked oligosaccharides, the glycan precursors employed in protein asparagine (N)-glycosylation. The assembly of dolichol-linked oligosaccharides begins on the cytosolic side of the endoplasmic reticulum membrane and finishes in its lumen. The sequential addition of sugars to dolichol pyrophosphate produces dolichol-linked oligosaccharides containing fourteen sugars, including two GlcNAcs, nine mannoses and three glucoses. Once assembled, the oligosaccharide is transferred from the lipid to nascent proteins by oligosaccharyltransferases. Dolichyl-phosphate beta-glucosyltransferase produces dolichyl beta-D-glucosyl phosphate/Dol-P-Glc, the glucose donor substrate used sequentially by ALG6, ALG8 and ALG10 to add glucose residues on top of the Man(9)GlcNAc(2)-PP-Dol structure. These are the three last steps in the biosynthetic pathway of dolichol-linked oligosaccharides to produce Glc(3)Man(9)GlcNAc(2)-PP-Dol. The enzyme is most probably active on the cytoplasmic side of the endoplasmic reticulum while its product Dol-P-Glc is the substrate for ALG6, ALG8 and ALG11 in the lumen of the endoplasmic reticulum.
Synonyms: bA421P11.2; PKD7
Tractability: Antibody: UniProt predicts a signal peptide or a membrane-spanning region. PROTAC: ubiquitination databases record sites on it; its protein half-life has been measured.
Gene: Protein-coding gene on chromosome 13 (36,949,738 to 37,000,763, reverse strand). Ensembl gene ENSG00000120697.
Subcellular location: Endoplasmic reticulum membrane
Subcellular location (Human Protein Atlas): Cytosol
Pathways (Reactome):
Metabolism of proteins: Synthesis of dolichyl-phosphate-glucose
Gene Ontology:
Molecular function: dolichyl-phosphate beta-glucosyltransferase activity; protein binding
Biological process: dolichol-linked oligosaccharide biosynthetic process; protein N-linked glycosylation
Cellular component: cytoplasmic side of endoplasmic reticulum membrane; cytoplasmic side of rough endoplasmic reticulum membrane; endoplasmic reticulum membrane; membrane
Genetic constraint (gnomAD): Loss-of-function variants: 13 observed, 25.11 expected, observed/expected ratio (o/e) 0.52, 90% interval 0.34 to 0.82. The upper end of that interval is the gene's LOEUF score, 0.82, which puts it in group 3 of 6, group 1 being the genes least tolerant of losing a copy. Missense variants: 224 observed, 280.77 expected, observed/expected ratio (o/e) 0.8, 90% interval 0.71 to 0.89. Synonymous variants: 113 observed, 102.28 expected, observed/expected ratio (o/e) 1.1, 90% interval 0.95 to 1.29.
Gene-disease validity (ClinGen):
ClinGen rates the evidence that ALG5 causes each of these diseases.
autosomal dominant polycystic kidney disease (autosomal dominant): Moderate. Autosomal dominant form of polycystic kidney disease.
Homologues: Orthologues: chimpanzee ALG5 (99% identical), dog ALG5 (94% identical), guinea pig ALG5 (93% identical), rabbit ALG5 (93% identical), pig ALG5 (92% identical), rat Alg5 (91% identical), macaque ALG5 (90% identical), mouse Alg5 (90% identical), tropical clawed frog alg5 (73% identical), zebrafish alg5 (72% identical), Drosophila melanogaster wol (57% identical), Caenorhabditis elegans algn-5 (44% identical). Paralogues in human: DPM1 (20% identical).
Diseases named in the same sentence as ALG5 in open-access papers:
ALG5 is named in the same sentence as 16 diseases in open-access papers, as found by Europe PMC text mining. Sharing a sentence is not in itself a finding about the gene and the disease. The quoted sentences say what the papers report.
liver cysts (2 papers, 2023 to 2024). "A recent study identified 5 monoallelic pathogenic variants in the ALG5 gene encoding ALG5 protein as a cause of ADPKD, with a phenotype including nonenlarged cystic kidneys, minimal liver cysts, and late-onset CKD progression to ESKD." (PMID 39081747, 2024). "Indeed, ALG5 is found in the ADPKD population without PLD, and ALG9 in individuals with ADPKD who also have liver cysts." (PMID 37628703, 2023).
polycystic kidneys (2 papers, 2023 to 2024). "In a cohort of genetically unresolved cases with polycystic kidneys, 17% revealed to be due to ALG5-CDG caused by monoallelic pathogenic ALG5 variants; 35% of the identified patients progressed to KF." (PMID 37597335, 2023). "Consistent with the one previous initial report of ALG5 variants, affected individuals showed nonenlarged polycystic kidneys, tubulointerstitial atrophy and fibrosis, and slowly progressive CKD." (PMID 39081747, 2024). "In this study, we describe 2 distant genetically related multiplex Irish families with nonenlarged polycystic kidneys and tubulointerstitial fibrosis caused by a novel monoallelic ALG5 variant and characterize its clinical, histopathologic, protein structural, and functional correlates." (PMID 39081747, 2024).
cystic kidney disease (1 paper, 2025). A congenital or acquired kidney disorder characterized by the presence of renal cysts. "About 30% of cystic kidney disease variants were found in patients aged > 75 years, including variants in 4 genes causing ADPKD-like disease spectrum (ALG5, ALG9, DNAJB11, and monoallelic IFT140)." (PMID 40677324, 2025).
cystic kidneys (1 paper, 2024). "We report a novel pathogenic ALG5 variant causing atypical cystic kidneys, tubulointerstitial fibrosis, and late-onset ESKD, which validates and complements the findings from the initial study identifying pathogenic ALG5 variants." (PMID 39081747, 2024).
ovarian tumour (1 paper, 2021). "In addition, ALG5 expression remains consistent across primary ovarian tumour, omental tissue and peritoneal diseases." (PMID 33473167, 2021).
Saul-Wilson syndrome (1 paper, 2023). "Some disorders have also been reclassified as CDG as the expansion of their pathophysiological mechanisms has included underlying glycosylation defects (e.g., Saul-Wilson syndrome [COG4], Cowden syndrome 7 [SEC23B], ALG5- and ALG9-CDG)." (PMID 37858231, 2023).
serous ovarian cancer (1 paper, 2022). "ALG5 was reported as a prognostic biomarker for early tumor progression in advanced high-grade serous ovarian cancer (HGSOC) ALG5." (PMID 35782861, 2022).
tumor (2 papers, 2021 to 2022). "We identified ALG5 as a prognostic biomarker for early tumour progression in advanced HGSOC despite CGR (HR = 2.42, 95% CI (1.57–3.75), p < 0.0001)." (PMID 33473167, 2021).
infection (1 paper, 2013). The state of being infected such as from the introduction of a foreign agent such as serum, vaccine, antigenic substance or organism. "Conversion from incident to older infection status among these 7 algorithms occurred first for Alg3 (gp41 band ≤0.5), tightly followed by Alg3.1 (gp41≤1) and Alg5 (p24≤0.5), Alg6 (p17≤0.5), Alg14, Alg2 (gp120≤1) and finally Alg4 (p31 = 0)." (PMID 23990968, 2013).
kidney diseases (1 paper, 2024). "In our investigation, we also sought to identify biomarkers for the biochemical diagnosis of ALG5 dysfunction and kidney disease progression." (PMID 39081747, 2024).
ALG5 also shares sentences with these, for which no sentence is quoted: autosomal dominant polycystic kidney disease (1 paper); Kidney Cyst (1); kidney failure (1); ovarian carcinoma (1); peritoneal diseases (1); viral infection (1).